VEGFA (vascular endothelial growth factor A)
Diseases named in the same sentence as VEGFA in open-access papers (continued):
Sharing a sentence is not in itself a finding about the gene and the disease.
cancer (continued). "BCL2, KRAS and VEGFA, most frequently mutated oncogenes in human cancer are overexpressed in different types of human malignancies." (PMID 28102286, 2017). "Neuropilin 1 has been implicated in cancer angiogenesis and metastasis because of its interaction with VEGFA." (PMID 29383201, 2017). "Evidence of the association between VEGFA polymorphisms and susceptibility to cancer (including PTC) has been shown in many previous investigations." (PMID 28178662, 2017). "As previously reported, VEGFA was confirmed to associate with promoting cancer stemness, and played an important role in the neovascularization of TSLCs." (PMID 28163656, 2017). "The oncogene VEGFA, encoding vascular endothelial growth factor A, induces proliferation and migration of vascular endothelial cells to promote angiogenesis in cancer." (PMID 29299133, 2017). "VEGFA is increased during oxidative stress and results in a compensatory increase in angiogenesis, a hallmark of cancer." (PMID 27887572, 2016). "Tailed mirtrons targeted against VEGFA mRNA, the misregulation of which is causative of several disorders including cancer, achieved significant levels of gene knockdown." (PMID 26089392, 2015). "This partially explains why cancer cells with high levels of VEGFA secretion are susceptible to hypoxia-induced ER stress." (PMID 26452217, 2015). "Overexpression of ID1 has been described in several cancers and has been specifically linked to increases in VEGFA gene transcription." (PMID 25207642, 2014). "Although cancer cells are the major source of VEGFA, cancer-associated stroma is also an important site of VEGFA production." (PMID 23203097, 2012). "In non-small cell lung cancer, a low VEGFA expression in cancer tissues was significantly associated with the presence of the −2578 CC, −634 GG and −1154 AA and GA genotypes." (PMID 23203097, 2012). "Two miRNAs, miR-126 and -205, were shown to regulate VEGFA expression and are implicated in a number of cancers, including lung, prostate and breast cancer." (PMID 23166713, 2012). "Primarily, we analyzed the molecular factors, such as HIF1A, EPAS1, and VEGFA gene expression levels, that could influence cancer risk and development." (PMID 39888575, 2026). "Pathway analysis linked these miRNAs to cancer-related processes like VEGFA-VEGFR2 signalling." (PMID 41168129, 2025). "For instance, interleukin (IL) 6 (IL-6), transforming growth factor beta (TGF-β), fibroblast growth factor 2 (FGF2), monocyte chemoattractant protein 1 (MCP-1), and vascular endothelial growth factor A (VEGFA) have been linked to the pre-cancer or initiation (formation) of HCC." (PMID 41219858, 2025). "In addition, the vascular endothelial growth factor gene (VEGFA), has also been linked to BC, since cancer cells require nutrients, oxygen, and the ability to eliminate waste products, where VEGFA is closely related." (PMID 39337657, 2024). "Also, CD274 (PD-L1) showed positive association with SIRPG, whereas RATE1E, CD276 and VEGFA expression seemed to be negatively correlated with SIRPG expression in a subset of TCGA cancers." (PMID 38833156, 2024). "Our data exposed the VEGFA level was increased in blood circulation after hUC-MSCs transplantation; whether the high VEGFA levels can cause cancer development remains unclear." (PMID 37777781, 2023). "We identified the overexpression of vascular endothelial growth factor-α (VEGFA)/β-catenin/matrix metalloproteinase (MMP)-7/Cluster of Differentiation 44 (CD44) in CRC to be associated with cancer progression, stemness, resistance to therapy, metastasis, and poor clinical outcomes." (PMID 36672201, 2023). "For 20 cancers, the expression of VEGFA was positively associated, except for KIRC, PRAD, and THCA." (PMID 37852616, 2023).
cancer (continued). "Regulation of genes that are known to be associated with cancer (VEGFA, DDX58/RIG1, MST1R/RON, BAGE, and TPTE) in anti‐TIF‐1γ+ patients, and their expression on protein level, however, need further investigation as these genes are also involved in other biological processes apart from tumorigenesis." (PMID 34043263, 2021). "VEGFA overexpression was previously reported to synergizes EGFR as one of the resistant mechanisms of BV therapy in other cancers, therefore it could explain why EGFR mutated OC had poorer PFS compared to EGFR wlidtype OC." (PMID 34477158, 2021). "3D co-cultures of HUVEC and cancer associated fibroblasts (CAFs) in a gel-based assay demonstrated that hypoxia (1% O2) promotes angiogenesis, and that secreted factors from hypoxia-treated CAFs, including VEGFA, are involved in this effect." (PMID 33525508, 2021). "Indeed, many of the TFs and chromatin modifiers identified amongst Etv6’s 540 direct target genes have previously been directly or indirectly implicated in the regulation of VegfA in endothelial and cancer cells." (PMID 30842454, 2019). "Thus, in addition to its angiogenic action, VEGFA upregulates Sox2 to drive stem cell expansion, together with miR-452 loss and Slug upregulation, providing a novel mechanism whereby cancer stem cells acquire metastatic potential." (PMID 28504716, 2017). "It would be of interest to investigate whether the adverse prognosis associated with the extent of macrophage infiltration in CRC and other cancer types overlaps with the aggressive nature of CRCs associated with VEGFA amplification." (PMID 28403223, 2017). "Within tumors, cancer cells and cancer-associated stroma are the major source of VEGFA." (PMID 29104726, 2017). "Thus, this site not only correlates with VEGFA expression, but plays a causative role in the reactivation of VEGFA in the blood cancer cells." (PMID 26886256, 2016). "Moreover, the predicted site does not only interact, but plays a causative role in controlling VEGFA activity in the cancer, as shown by the genome-editing experiments." (PMID 26886256, 2016). "In addition, we found that restoration of miR137 expression down-regulates expression of VEGFA, an AR target gene, which suggests a role of miR137 loss also in cancer angiogenesis." (PMID 26461474, 2015). "Vascular endothelial growth factor A (VEGF-A) is one of the most effective biologic inducers of angiogenesis, which is highly expressed in a wide variety of human cancers and is associated with cancer progression, invasion and metastasis, and poor patient prognosis." (PMID 23800091, 2013). "In addition, other well-known cancer-associated genes (including VEGFA, DUSP9 and ERBB4) were also selectively validated as exhibiting consistently disrupted expression patterns in most of the ccRCC samples profiled." (PMID 21253009, 2010). "On the other hand, the expression of VEGFA was significantly higher in post-menopausal cancer patients (p = 0.0042)." (PMID 39888575, 2026). "This in turn suggested a diminished cancer-driving effect of VEGFA in the setting of the combinatorial alterations tested." (PMID 40721510, 2026). "In cancer-affected tissue, significant correlations of VEGFA with HIF1A and EPAS1 were weak and only in post-menopausal cases." (PMID 39888575, 2026). "HIF1A and VEGFA gene expression (p = 0.0199 and p = 0.0239, respectively) differed significantly between the control and cancer groups in pre-menopausal women." (PMID 39888575, 2026). "Inhibition of the MAPK/JNK signaling pathway resulted in suppressed TAM recruitment, M2 TAM polarization, and IL-8 and VEGFA production and secretion by cancer cells." (PMID 39972459, 2025).
cancer (continued). "High levels of MMP28 promote the secretion of IL-8 and VEGFA by cancer cells by mediating the phosphorylation of the MAPK/JNK signalling pathway and then recruiting TAMs." (PMID 39972459, 2025). "I-DXd, in particular, possesses the dual capability of direct cancer cell ablation through antigen recognition and the ancillary eradication of protumor VEGFA+ neutrophils (TANs), which contributes to a more immunologically favorable TME." (PMID 39971940, 2025). "Our results provide proof of the concept that HER2-VEGFA BsAbs achieve enhanced antitumor activity by leveraging HER2 overexpressed on the cancer cell surface to induce co-phagocytosis of VEGFA." (PMID 40906526, 2025). "Findings regarding hsa-miR-21-5p and its interaction with hypoxia-inducible factors HIF1A and HIF2A or its influence on VEGFA signaling highlight its impact on cancer progression and therapeutic implications." (PMID 40362695, 2025). "Epidermal growth factor receptor (EGFR) and vascular endothelial growth factor A (VEGF-A) have been shown to contribute to cancer cell survival and have been identified as potential therapeutic targets for advanced OC." (PMID 40969763, 2025). "HER2-VEGFA BsAb induces co-phagocytosis of fibroblast-secreted VEGFA with HER2-overexpressing cancer cells via ADCP in co-cultures with macrophages." (PMID 40906526, 2025). "In the TME, hypoxic cancer cells, neutrophils, and other cells secrete vascular endothelial growth factor A (VEGFA) acts through their cognate receptors on the endothelium and blocks the expression of adhesion molecules, preventing T-cell infiltration." (PMID 40180890, 2025). "In cancer cells, a decreased VEGFA expression directly affects blood vessel formation and maturation." (PMID 41294859, 2025). "VEGFA is mainly produced by cancer cells; however, subpopulations of TAMs secrete VEGFA to form microvessels in tumors." (PMID 39985645, 2025). "Our results indicated that VEGFA was secreted more than three-fold (p < 0.0001) in HIF1α over-expressed condition compared to wild type cancer cells, whereas after combinatorial treatment it was back to normal." (PMID 40045186, 2025). "The success of angiogenesis inhibitors has confirmed VEGFA as a pivotal clinical target, crucial for patients with late-stage cancers who have limited treatment options." (PMID 40316995, 2025). "VEGFA in cancer-derived EVs was reported to be inaccessible to anti-VEGFA antibodies and to exert an effect via intracrine signaling in ECs." (PMID 40662366, 2025). "Cytokine antibody array analysis revealed that MMP28 knockdown suppressed the production and release of IL-2, IL-5, IL-8, MCP-1, and VEGFA by cancer cells." (PMID 39972459, 2025). "In brief, VEGFA, central to vascular processes, is targeted in cancer and eye diseases through antibodies, decoy receptors, or inhibitors." (PMID 40050849, 2025). "Transcription factors play a critical role in regulating VEGFA expression, with STAT3 recognized for its ability to activate VEGFA in cancer cells." (PMID 40474298, 2025). "VEGFA, IL-10, and prostaglandin E2, produced by cancer cells, collectively induce the upregulation of FasL in TECs." (PMID 40136652, 2025). "Vascular endothelial growth factor‐A (VEGF‐A) is recognized as a key mediator in cancer pathophysiology due to its potent angiogenic properties." (PMID 40944395, 2025). "The miR-205-5p exhibits a significant anti-angiogenic effect by targeting VEGFA, as demonstrated in several types of cancers." (PMID 40002404, 2025). "Although VEGFA serves as a central mediator in both cancer and ocular neovascular diseases, the unique microenvironment of the retina, coupled with the specialized functions of RPE cells, introduces specific complexities." (PMID 40002404, 2025). "Research has demonstrated that ZNF24 functions as a transcriptional inhibitor in various cancers by repressing VEGFA transcription." (PMID 40274778, 2025).
cancer (continued). "This study introduces JS207, a novel BsAb targeting PD-1 and VEGFA, engineered to overcome resistance mechanisms in cancer therapy by concurrently inhibiting immunosuppressive and angiogenic pathways." (PMID 40607397, 2025). "We demonstrated that modulating MMP28 expression altered the secretion of IL-8 and VEGFA by cancer cells, subsequently affecting TAM recruitment and M2 polarization." (PMID 39972459, 2025). "These cells colocalized in a hypoxic and VEGFA-rich niche that harbored abundant cancer cells and APLNhi endothelial tip cells." (PMID 41203997, 2025). "In summary, the discovery that B-9-3 inhibits angiogenesis by targeting the VEGFA/PI3K/AKT signaling pathway provides a robust theoretical basis for the development of novel multi-mechanistic anti-cancer agents." (PMID 40432889, 2025). "HER2-VEGFA BsAb induces co-phagocytosis of recombinant VEGFA with HER2-overexpressing cancer cells via ADCP in co-cultures with primary bone marrow–derived macrophages." (PMID 40906526, 2025). "In step 2, the anchored VEGFA is phagocytized along with the targeted cancer cells by RAW264.7 macrophages via ADCP induced by TG-VHS." (PMID 40906526, 2025). "In step 1, soluble VEGFA in the medium is anchored onto cancer cells following bispecific binding of TG-VHS to VEGFA and HER2." (PMID 40906526, 2025). "The silencing of MTDH significantly lowered proteins found in gene sets involved in cancer-related pathways such as VEGFA-VEGFR2 and EGF-EGFR signaling, which are crucial for angiogenesis and cell proliferation." (PMID 41286067, 2025). "Particularly, VEGFB, which is a newly identified target sharing similar structures with VEGFA, exhibited enhanced expression level in cancer cells." (PMID 38944814, 2024). "Inhibitors of the interaction between Neuropilin-1 (NRP-1) and Vascular Endothelial Growth Factor-A165 (VEGF-A165) hold significant promise as therapeutic and diagnostic agents directed against cancers overexpressing NRP-1." (PMID 39181965, 2024). "In the decade following the discovery of VEGFA, inhibition of VEGFA in animal models of cancer demonstrated improved outcomes." (PMID 39087477, 2024). "Our findings emphasize the significance of HIF-1α, VEGFa, NF-κB and Gal-1 signaling pathways in the implementation of novel treatment techniques against drug-resistant cancers; especially sorafenib-resistant ones." (PMID 39152108, 2024). "ACE2 directly inhibited cancer angiogenesis, cell growth and VEGFA (vascular endothelial growth factor A) expressions in A549 in vitro and in vivo." (PMID 39273283, 2024). "Collectively, these data showed that the VEGFA/NRP-1/GAPVD1 axis is involved in the regulation of cancer stemness and mobility in TNBC cells and that GAPVD1 acts as an effector downstream of NRP-1 in this process." (PMID 38169627, 2024). "EnrichR pathway enrichment analysis coupled with Wiki Pathway datasets revealed pathways regulating multiple cellular processes that are commonly upregulated in cancers, such as VEGFA-VEGFR2 Signaling, PI3K-Akt signaling, and EGF/EGFR signaling." (PMID 38464090, 2024). "Our study underscores the crosstalk between TNBC cells and TAMs mediated by VEGFA and further clarifies the role and underlying mechanisms of the VEGFA/NRP-1/GAPVD1 axis in regulating cancer stemness." (PMID 38169627, 2024). "The results revealed that VEGFA was up-regulated in several cancer types, including BRCA, but downregulated in KIRP, PRAD and THCA." (PMID 39508048, 2024). "More importantly, previous studies have emphasized the importance of the ratio of TNF+ MCs to VEGFA+ MCs for their cancer type-specific functions, and our data revealed that MC2 MCs and MC4 MCs correspond to these two populations." (PMID 39840068, 2024). "Our present results showed that VEGFA produced by TAMs promoted the cancer stemness of TNBC cells via the NRP-1 receptor and the downstream GAPVD1/Wnt/β-catenin signaling pathway." (PMID 38169627, 2024).
cancer (continued). "In this review, we have outlined the recent advancements in immunotherapy for advanced GC, including immune checkpoint inhibitors, cancer vaccines, vascular endothelial growth factor-A inhibitors, and chimeric antigen receptor T-cell therapy." (PMID 38339311, 2024). "Because originally NRP1 has been established as a key regulator in EC of VEGFA signalling, many approaches have been used to inhibit NRP1 binding to VEGFA as a potential therapeutic target to prevent angiogenesis in cancer and neovascular eye diseases." (PMID 38323651, 2024). "Above all, our data support and broaden the concept that the VEGFA/NRP-1/GAPVD1 axis targets the downstream Wnt/β-catenin signaling pathway in regulating cancer stemness in TNBC cells." (PMID 38169627, 2024). "In cancer, pathological angiogenesis is mediated by the vascular endothelial growth factor A (VEGFA) and angiopoietin-2 (ANGPT2), which both constitute good targets of anti-angiogenic therapies." (PMID 38903504, 2024). "In this study, we analyzed TCGA transcriptome data to evaluate VEGFA expression across various cancers and normal tissues." (PMID 39508048, 2024). "Expression based on individual cancer stages showed that VEGFA and VEGFB were highly expressed in patients with stage 4 cancer." (PMID 38426619, 2024). "The data showed that miR-664a-3p was mainly distributed in the PDAC cancer stroma, including fibrous tissues and vessels, and was positively correlated with VEGFA." (PMID 38035445, 2024). "In this study, we found that M2-type TAMs expressed high levels of VEGFA and promoted the migration, invasion and cancer stemness of TNBC cells by secreting VEGFA." (PMID 38169627, 2024). "VEGFA, in particular, has been extensively studied and is found to be overexpressed in a majority of human cancers." (PMID 39606802, 2024). "As to VEGFA, we showed that VEGFA produced by TAMs promoted the cancer stemness of TNBC cells via the NRP-1 receptor and downstream GAPVD1/Wnt/β-catenin signaling pathway." (PMID 38169627, 2024). "Nowadays, immunotherapies against advanced GC include ICIs, adoptive cell therapy, cancer vaccines, vascular endothelial growth factor A (VEGFA), and antibody anti-chimeric antigen receptor (CAR-T)." (PMID 38787209, 2024). "We found that increased expression of VEGFA in cancer cells of the three types of programs, mediated the benefits of Bevacizumab treatment, a humanized monoclonal antibody against VEGFA, in ccRCC treatment." (PMID 38944814, 2024). "Many other factors have a similar function to VEGFA in cancer angiogenesis, such as PIGF, fibroblast growth factor (FGF), hypoxia-inducible factor (HIF) -1α and HIF-2α, and platelet-derived growth factor (PDGF)." (PMID 38611042, 2024). "It effectively suppressed the secretion of vascular endothelial growth factor A (VEGF-A) and interleukin 6 (IL-6) from cancer cells." (PMID 38535455, 2024). "For example, SCR of VEGFA results in reduced angiogenesis, which can be beneficial in the treatment of cancerous tumors and retinopathies." (PMID 38499809, 2024). "The pro-angiogenic factor vascular endothelial growth factor A (VEGFA) promotes the proliferation of vascular endothelial cells and has been implicated in the progression and metastasis of various cancers." (PMID 39012409, 2024). "CCND1 (Cyclin D1), MPP2 (Membrane palmitoylated protein 2), Bax, Bcl2, HIF1A and VEGFA are transcriptionally regulated molecules that are related to cell proliferation, apoptosis and cancer cell invasion and metastasis processes." (PMID 39834948, 2024). "In the present study, we report that M2-type TAMs promote the cancer stemness of TNBC cells through the secretion of VEGFA." (PMID 38169627, 2024). "The Kyoto Encyclopedia of Genes and Genomes (KEGG) analysis showed that those genes were enriched in many cancer‐related signaling pathways, including “PD‐L1 expression and PD‐1 checkpoint pathway in cancer” and “VEGFA‐signaling pathway”." (PMID 38247171, 2024).